RNU7-153P (RNA, U7 small nuclear 153 pseudogene)
Gene: Small nuclear RNA gene on chromosome 8 (14,319,455 to 14,319,516, forward strand). Ensembl gene ENSG00000252264.
Homologues: Orthologues: chimpanzee U7 (97% identical), macaque U7 (94% identical). Paralogues in human: RNU7-99P (81% identical), RNU7-1 (79% identical), RNU7-37P (79% identical), RNU7-11P (77% identical), RNU7-129P (77% identical), RNU7-3P (77% identical), RNU7-47P (77% identical), RNU7-65P (77% identical), RNU7-79P (77% identical), RNU7-9P (77% identical), U7 (77% identical), RNU7-123P (76% identical), and 142 more.